RLBP1 (retinaldehyde binding protein 1)
Description:
Soluble retinoid carrier essential the proper function of both rod and cone photoreceptors. Participates in the regeneration of active 11-cis-retinol and 11-cis-retinaldehyde, from the inactive 11-trans products of the rhodopsin photocycle and in the de novo synthesis of these retinoids from 11-trans metabolic precursors. The cycling of retinoids between photoreceptor and adjacent pigment epithelium cells is known as the 'visual cycle'.
Synonyms: CRALBP
Tractability: Small molecule: a structure with a bound ligand is known; it has a binding pocket of medium quality. PROTAC: its protein half-life has been measured.
Gene: Protein-coding gene on chromosome 15 (89,209,869 to 89,222,577, reverse strand). Ensembl gene ENSG00000140522.
Subcellular location: Cytoplasm
Subcellular location (Human Protein Atlas): Cytosol; Centrosome; Nucleoplasm
Pathways (Reactome):
Sensory Perception: The canonical retinoid cycle in rods (twilight vision); The retinoid cycle in cones (daylight vision)
Disease: Defective visual phototransduction due to RDH5 loss of function
Gene Ontology:
Molecular function: protein binding; phosphatidylinositol bisphosphate binding; 11-cis retinal binding
Biological process: visual perception; vitamin A metabolic process
Cellular component: cytosol; cell body; cytoplasm
Genetic constraint (gnomAD): Loss-of-function variants: 26 observed, 37.82 expected, observed/expected ratio (o/e) 0.69, 90% interval 0.5 to 0.95. The upper end of that interval is the gene's LOEUF score, 0.95, which puts it in group 4 of 6, group 1 being the genes least tolerant of losing a copy. Missense variants: 410 observed, 410.88 expected, observed/expected ratio (o/e) 1, 90% interval 0.92 to 1.08. Synonymous variants: 155 observed, 159.7 expected, observed/expected ratio (o/e) 0.97, 90% interval 0.85 to 1.11.
Gene-disease validity (ClinGen):
ClinGen rates the evidence that RLBP1 causes each of these diseases.
RLBP1-related retinopathy (autosomal recessive): Definitive. A retinopathy caused by bialleleic variants in the RLBP1 gene, often involving flecks in the retina.
Homologues: Orthologues: chimpanzee RLBP1 (99% identical), macaque RLBP1 (99% identical), dog RLBP1 (91% identical), rabbit RLBP1 (91% identical), rat Rlbp1 (91% identical), guinea pig RLBP1 (91% identical), mouse Rlbp1 (91% identical), pig RLBP1 (86% identical), tropical clawed frog rlbp1 (75% identical), zebrafish rlbp1b (68% identical), zebrafish rlbp1a (65% identical), Drosophila melanogaster CG33514 (21% identical), and 12 more. Paralogues in human: CLVS1 (35% identical), CLVS2 (34% identical), TTPAL (30% identical).
Diseases named in the same sentence as RLBP1 in open-access papers:
RLBP1 is named in the same sentence as 41 diseases in open-access papers, as found by Europe PMC text mining. Sharing a sentence is not in itself a finding about the gene and the disease. The quoted sentences say what the papers report.
retinitis punctata albescens (11 papers, 2015 to 2025). "Mutations in RLBP1 lead to retinitis punctata albescens and Bothnia dystrophy, highlighting the critical role of retinoid chaperones." (PMID 41463332, 2025). "Mutations in RLBP1 disrupt ligand binding and produce a spectrum of phenotypes, including FA, retinitis punctata albescens, and Bothnia dystrophy." (PMID 41463332, 2025). "Mutations in RLBP1 are associated with recessively inherited clinical phenotypes, including Bothnia dystrophy, retinitis pigmentosa, retinitis punctata albescens, fundus albipunctatus, and Newfoundland rod–cone dystrophy." (PMID 34668483, 2021). "Among these, the retinaldehyde-binding protein 1 (RLBP1) mutations are cause of retinitis punctata albescens (RPA, OMIM#136880)." (PMID 28764803, 2017). "Mutations in RLBP1 have been associated with a group of autosomal recessive retinal diseases comprising autosomal recessive retinitis pigmentosa, Bothnia dystrophy, Newfoundland rod–cone dystrophy, retinitis punctata albescens (RPA), and fundus albipunctatus." (PMID 34668483, 2021). "Mutation of RLBP1 is associated with several inherited retinal disorders, such as Bothnia dystrophy, newfoundland rod-cone dystrophy, retinitis pigmentosa, and retinitis punctata albescens." (PMID 32378698, 2020). "Katsanis end coworkers (2001) found a p.Arg150Gln mutation in the RLBP1 gene in a consanguineous Saudi Arabian kindred with a retinal dystrophy phenotype that fulfilled the criteria of FA in younger individuals and retinitis punctata albescens in older patients." (PMID 25820994, 2015). "However, retinitis punctata albescens due to RLBP1 mutation (Bothnia dystrophy) may be more difficult to distinguish, as in the early stages, there is phenotypic overlap with FA." (PMID 25820994, 2015).
retinitis pigmentosa (10 papers, 2016 to 2024). Retinitis pigmentosa (RP) is an inherited retinal dystrophy leading to progressive loss of the photoreceptors and retinal pigment epithelium and resulting in blindness usually after several decades. "NEI-VFQ is ubiquitous but problematic in IRDs due to its multi-dimensionality, lack of documented content validity, and demonstrated poor fit for RLBP1-associated retinitis pigmentosa." (PMID 39120885, 2024). "RLBP1 retinitis pigmentosa (RLBP1 RP) is an autosomal recessive form of retinitis pigmentosa (RP), caused by biallelic mutations of the RLPB1 gene on chromosome 15." (PMID 32372289, 2020). "Mutations in RLBP1, the gene encoding CRALBP in humans, results in retinitis pigmentosa and mutations in a gene encoding αTTP results in ataxia with vitamin E deficiency (AVED)." (PMID 29136137, 2017). "RLBP1 RP is an autosomal recessive form of retinitis pigmentosa (RP), characterized by night blindness, prolonged dark adaptation, constricted visual fields and impaired macular function." (PMID 32372289, 2020). "Interestingly, RGR, CNGA1, and RLBP1 play an important role in retinitis pigmentosa." (PMID 37179305, 2023).
retinal degeneration (6 papers, 2017 to 2024). Degeneration of the retina. "CRALBP is encoded by Retinaldehyde-binding protein 1 (RLBP1) gene and mutations in RLBP1 lead to an autosomal recessive form of retinal degeneration." (PMID 37728589, 2024). "RLBP1 RP is associated with progressive loss of vision due to retinal degeneration and is a rare disease, with only 152–160 cases worldwide reported in the literature." (PMID 32372289, 2020). "Though RLBP1 RP is limited only to retinal degeneration, it affects patients’ ability to perform vision-dependent functions of everyday life and has a profound effect on physical, social and psychological wellbeing." (PMID 32372289, 2020). "Mutations in retinaldehyde-binding protein 1 (RLBP1), encoding the visual cycle protein cellular retinaldehyde-binding protein (CRALBP), cause an autosomal recessive form of retinal degeneration." (PMID 32188692, 2020). "Furthermore, RLBP1 exhibits relevant eye phenotypes in mice (‘retinal degeneration’, ‘decreased retinal photoreceptor cell number’)." (PMID 29529059, 2018).
Rod-cone dystrophy (6 papers, 2018 to 2024). An inherited retinal disease subtype in which the rod photoreceptors appear to be more severely affected than the cone photoreceptors. "Mutations in RPE65 and RLBP1 typically lead to slow progressing rod-cone dystrophies and therefore, the application of effective therapies during early disease presentation could preserve remaining photoreceptor structural integrity and retain functional vision." (PMID 29696141, 2018). "Retinal dystrophy (RD) caused by biallelic mutations in the Retinaldehyde-binding protein 1 (RLBP1) gene, is an autosomal recessive rod-cone dystrophy that affects approximately 10,000 individuals worldwide." (PMID 39256350, 2024).
retinal disease (5 papers, 2007 to 2023). "known retinal disease genes (BEST1 [NM_004183], C1QTNF5 [NM_015645], CDH3 [NM_001793], LRAT [NM_004744], RDH5 [NM_002905], RDH11 [NM_016026], RGR [NM_002921], RLBP1 [NM_000326] and STRA6 [NM_022369])." (PMID 20479888, 2010).
Retinal dystrophy (3 papers, 2022 to 2024). Retinal dystrophy is an abnormality of the retina associated with a hereditary process. "In conclusion, to date, AAV8-RLBP1 has shown preliminary safety and efficacy in patients with RLBP1-associated retinal dystrophy." (PMID 39256350, 2024). "Within the spectrum of RP-related retinal dystrophy, several gene therapy studies have been published for the replacement of specific mutated genes, such as RPGR MERTK, RLBP1 and PDE6B." (PMID 37762059, 2023).
Atrophy (2 papers, 2020 to 2024). Any weakening or degeneration, especially through lack of use. "The involvement of RPE in the atrophy associated with RLBP1/CRALBP disease is indicated in other studies by the hyperfluorescence observed in fluorescein angiograms and by the same hypertransmission of SD-OCT signal into the choroid at sites of atrophy." (PMID 32188692, 2020).
congenital stationary night blindness (2 papers, 2021 to 2025). "Variants in LRIT3, GRK1, and RLBP1 were previously reported to be associated with autosomal recessive or X-linked congenital stationary night blindness." (PMID 40365019, 2025). "RPE65 and RLBP1, which were highly and specifically expressed in the P4 cluster, are susceptible genes contributing to RP and congenital stationary night blindness (CSNB)." (PMID 34977041, 2021).
Newfoundland rod-cone dystrophy (2 papers, 2017 to 2020). "About RLBP1 gene, different mutations are linked to a wider spectrum of phenotype as Bothnia retinal dystrophy (BD), Newfoundland rod-cone dystrophy (NFRCD), and fundus albipunctatus (FA)." (PMID 28764803, 2017).
night blindness (2 papers, 2020 to 2023). Inability to see clearly in dim light. "Key symptoms of RLBP1 RP such as night blindness, and difficulty adapting to changes in lighting, also had equivalent relevance in the distal RP/LCA sample included within this study." (PMID 37466759, 2023). "RLBP1 RP is characterized by severe night blindness from childhood due to prolonged dark adaptation, constricted visual fields (VF) and reduced macular function with decreasing visual acuity (VA) in early adulthood." (PMID 32372289, 2020).
Autoimmunity (1 paper, 2014). The occurrence of an immune reaction against the organism's own cells or tissues. "Both elevated seroreactivity to RBP3 and RLBP1 in AMD patients suggests that the inflammation, in particular, autoimmunity, is strongly associated with the pathogenesis of the disease." (PMID 25488058, 2014).
neuroblastoma (1 paper, 2008). Neuroblastoma (NB) is the most common solid, extracranial childhood tumor. "Six experimental constructs (GLUL 500±UTR, RLBP1 500±UTR, and S100b 500±UTR) were tested by transfection in 3 cell types: wMC Muller cells, NIH/3T3 fibroblasts, and Neuro-2a neuroblastoma cells." (PMID 18437242, 2008).
oral cancer (1 paper, 2020). "In oral cancer, the over expression of RLBP1 is associated with increased glucose uptake and aerobic glycolysis-mediated ATP synthesis." (PMID 32378698, 2020).
Visual impairment (1 paper, 2024). "Visual impairment due to RLBP1-RD has a substantial impact on physical functioning and daily activities." (PMID 39256350, 2024).
retinal disorder (5 papers, 2014 to 2022). Any disease or disorder of the retina. "Here we report findings in two siblings with early-onset retinal disorders who were compound heterozygous for two pathogenic mutations in the RLBP1 gene." (PMID 32188692, 2020). "This occurs, for example, in vitamin A deficiency, fundus albipunctatus (RDH5-retinopathy) and Oguchi disease (SAG- or GRK1-retinopathy) and in some cases of rod-cone dystrophy including early stages of Bothnia dystrophy (RLBP1-retinopathy)." (PMID 29934801, 2018).
RLBP1 also shares sentences with these, for which no sentence is quoted: uveitis (6 papers); autoimmune uveitis (5); tumor (5); cancer (3); diabetes (3); autosomal recessive retinitis pigmentosa (2); Rb (2); Ataxia (1); autosomal recessive rod-cone dystrophies (1); COVID-19 (1); diabetic retinopathy (1); glaucoma (1); glioma (1); Hyperglycemia (1); invasive breast carcinoma (1); iritis (1); Leber congenital amaurosis (1); melanoma (1); metastatic melanoma (1); microphthalmia (1); posterior uveitis (1); Retinal atrophy (1); retinal tumors (1); stomach cancer (1); Usher syndrome (1); vitritis (1).